INSYN2B (inhibitory synaptic factor family member 2B)
Synonyms: C5orf57; FAM196B
Tractability: No criterion of Open Targets' tractability assessment is met for any kind of drug.
Gene: Protein-coding gene on chromosome 5 (169,861,303 to 169,980,495, reverse strand). Ensembl gene ENSG00000204767.
Genetic constraint (gnomAD): Loss-of-function variants: 16 observed, 43.08 expected, observed/expected ratio (o/e) 0.37, 90% interval 0.25 to 0.56. The upper end of that interval is the gene's LOEUF score, 0.56, which puts it in group 2 of 6, group 1 being the genes least tolerant of losing a copy. Missense variants: 608 observed, 674.57 expected, observed/expected ratio (o/e) 0.9, 90% interval 0.84 to 0.96. Synonymous variants: 245 observed, 257.44 expected, observed/expected ratio (o/e) 0.95, 90% interval 0.86 to 1.06.
Homologues: Orthologues: chimpanzee INSYN2B (99% identical), macaque INSYN2B (94% identical), rabbit INSYN2B (86% identical), pig INSYN2B (86% identical), dog INSYN2B (85% identical), guinea pig INSYN2B (78% identical), mouse Insyn2b (78% identical), rat Insyn2b (67% identical), tropical clawed frog insyn2b (39% identical). Paralogues in human: INSYN2A (20% identical).
Diseases named in the same sentence as INSYN2B in open-access papers:
INSYN2B is named in the same sentence as 1 disease in open-access papers, as found by Europe PMC text mining. Sharing a sentence is not in itself a finding about the gene and the disease. The quoted sentences say what the papers report.
tumor (1 paper, 2025). "Additionally, analysis of macrophages identified recently described sub-types of tumor-associated macrophages (TAMs), as well as a small cluster, which we named Insyn2b-TAMs based on marker expression." (PMID 39841099, 2025).